FABP2 (fatty acid binding protein 2)
Diseases named in the same sentence as FABP2 in open-access papers (continued):
Sharing a sentence is not in itself a finding about the gene and the disease.
Nephropathy (5 papers, 2015 to 2024). A nonspecific term referring to disease or damage of the kidneys. "Canani LH etal’s study showed that the fatty acid-binding protein-2 (FABP2) Ala54Thr polymorphism was associated with renal disease in patients with T2D." (PMID 25802555, 2015). "The aim of this study was to investigate the relation of circulating FABP1 and FABP2 levels to nephropathy in patients with T2DM." (PMID 32922199, 2020). "This suggests that the concentration of plasma FABP2 increases with the progression of kidney disease." (PMID 32922199, 2020). "The results of this study suggest that endotoxin and FABP2/I-FABP may be used for indicating intestinal damage, creatinine for kidney damage, and AST and FABP1/L-FABP for liver damage during the post-REBOA phase." (PMID 34211011, 2021). "The mean FABP1 and FABP2 levels increased parallel to the severity of nephropathy." (PMID 32922199, 2020). "The purpose of the present study was to investigate the levels of FABP1 and FABP2 in T2DM patients in various stages of nephropathy to clarify the role of FABP1 and FABP2 in the pathogenesis of diabetic nephropathy." (PMID 32922199, 2020).
Hyperinsulinemia (4 papers, 2020 to 2023). An increased concentration of insulin in the blood. "FABP2-knockout did not cause death of mice, but their weight would change with a hyperinsulinemia, but FABP2 was not necessary for dietary fat absorption." (PMID 36683854, 2022).
non-alcoholic fatty liver disease (4 papers, 2018 to 2025). "Fabp2 (also known as I-FABP), belongs to the FA-binding protein family, which participates in FA metabolism 43 and nonalcoholic fatty liver disease development." (PMID 39664586, 2024). "Dysregulation was established for FABP3 in cardiovascular disorders, FABP1, FABP2, FABP4 and FABP5 in non-alcoholic fatty liver disease and FABP5 and FABP7 in cancer." (PMID 30386187, 2018).
diabetic nephropathy (3 papers, 2020 to 2024). "The cross-sectional design limits our ability to infer a causal relationship between increased plasma FABP1 and FABP2 levels and diabetic nephropathy." (PMID 32922199, 2020). "Studies with long-term follow-up are needed to clarify the role of FABP1 and FABP2 in association with diabetic nephropathy." (PMID 32922199, 2020). "Increasing concentrations of FABP1 and FABP2 were independently and significantly associated with diabetic nephropathy." (PMID 32922199, 2020). "Increasing levels of FABP1 and FABP2 showed a significant linear trend and were independently associated with diabetic nephropathy, especially when concentrations were analyzed both by tertile and by a continuous variable." (PMID 32922199, 2020). "Multiple logistic regression analysis revealed FABP1 and FABP2 as an independent association factor for diabetic nephropathy, even after full adjustment of known biomarkers." (PMID 32922199, 2020). "A plasma FABP2 concentration of >2.8 ng/mL was associated with diabetic nephropathy, with a sensitivity of 48.2% and specificity of 85.6% (data not shown)." (PMID 32922199, 2020). "In conclusion, this study demonstrated that plasma FABP1 and FABP2 levels were significantly associated with diabetic nephropathy." (PMID 32922199, 2020). "The plasma FABP1 and FABP2 concentrations were significantly associated with diabetic nephropathy even after controlling for anthropometric variables, fasting glucose, lipid profile, and smoking status." (PMID 32922199, 2020). "Furthermore, receiver operating characteristic curve analysis showed that a FABP1 level of >33.8 ng/mL and a FABP2 level of >2.8 ng/mL were associated with diabetic nephropathy." (PMID 32922199, 2020). "Moreover, an increased concentration of plasma FABP1 and FABP2 was associated with diabetic nephropathy, even in a fully adjusted model." (PMID 32922199, 2020). "Furthermore, the ROC curves of FABP1 and FABP2 concentrations showed that a FABP1 concentration of >33.8 ng/mL was associated with diabetic nephropathy and a FABP2 concentration of >2.8 ng/mL were associated with diabetic nephropathy." (PMID 32922199, 2020). "Finally, whether increased FABP2 levels are associated with diabetic nephropathy requires further research." (PMID 32922199, 2020). "Demographic and potential metabolic confounding factors were analyzed with logistic regression to calculate the effects of FABP1 and FABP2 levels on diabetic nephropathy." (PMID 32922199, 2020). "We found high plasma levels of FABP2 in our patients with diabetic nephropathy." (PMID 32922199, 2020). "In addition, the ROC curve to detect of diabetic nephropathy revealed an AUC of 0.690 (95% CI: 1.302-1.976, p <0.0001) for FABP2." (PMID 32922199, 2020). "FABP1 and FABP2 could be novel biomarkers of diabetic nephropathy." (PMID 32922199, 2020). "Although the use of plasma FABP2 level as a single surrogate biomarker to predict diabetic nephropathy will be limited, it may be useful as one indicator in a multi-marker panel such as in combination with plasma FABP1 to better assess individuals suspected of having diabetic nephropathy." (PMID 32922199, 2020).
enteritis (3 papers, 2022 to 2024). Inflammation of the small intestine. "To our knowledge, correlations of gut FABP2 levels with serum IFABP levels have not been described, but we hypothesize that increased expression might be a compensatory mechanism triggered by enteritis." (PMID 35347206, 2022).
heart failure (3 papers, 2011 to 2024). Inability of the heart to pump blood at an adequate rate to meet tissue metabolic requirements. "Furthermore, fatty acid binding protein 2 (FABP2) is related to lipid metabolism, whereas the N-terminal prohormone of brain natriuretic peptide (NTproBNP) is a well-known marker of heart failure, but less known for its role in insulin sensitivity." (PMID 38921470, 2024).
hepatocellular carcinoma (3 papers, 2022 to 2023). A malignant tumor that arises from hepatocytes. "For example, FABP2 is highly expressed in gastric cancer, whereas high FABP3 expression has been associated with poor prognosis in patients with hepatocellular carcinoma (HCC) and esophageal cancer." (PMID 35783014, 2022).
Renal insufficiency (3 papers, 2017 to 2022). A reduction in the level of performance of the kidneys in areas of function comprising the concentration of urine, removal of wastes, the maintenance of electrolyte balance, homeostasis of blood pressure, and calcium metabolism. "Accordingly, clinicians and researchers should consider using FABP2 as a diagnostic and prognostic marker in patients with renal insufficiency." (PMID 32922199, 2020). "Although it can be removed by renal replacement therapy, FABP2 levels in patients with renal insufficiency are usually elevated." (PMID 32922199, 2020). "Recently, FABP2 has been shown to be a reliable marker of acute intestinal ischemia, including nonocclusive mesenteric ischemia 13, for which renal failure and hemodialysis are well known major risk factors 34,35." (PMID 32922199, 2020).
Type 1 Diabetes (3 papers, 2022 to 2025). "We previously showed that FABP2 and PGN were elevated in the plasma of individuals with type 1 diabetes." (PMID 39875729, 2025). "Subsequently, we examined the association of gut-regulated components of the immune system, gut leakage markers (FABP2 and peptidoglycan) and angiotensin II in individuals with type 1 diabetes with and without diabetic retinopathy compared with control individuals." (PMID 39875729, 2025).
Abdominal obesity (2 papers, 2016 to 2024). Excessive fat around the stomach and abdomen. "In a dominant model, the rare allele of rs1799883 (FABP2) (GA/AA vs GG) was associated with prevalence of high triglycerides levels (OR 2.22; P = 0.014) but not with prevalence of abdominal obesity (OR 1.67; P = 0.033) and MetS (OR 1.59; P = 0.068)." (PMID 27684940, 2016). "After the washout period and the initiation of a longer 4-week supplementation, we observed that FABP2 decreased in both groups (significant in crossover kale) and this could be due to reduced food intake secondary to modestly improved measures of central obesity." (PMID 39114118, 2024).
bladder cancer (2 papers, 2008 to 2025). "FABP2 gene mutations have been identified as molecular markers of urothelial carcinoma and may aid in the early detection of bladder cancer." (PMID 40717587, 2025).
coccidiosis (2 papers, 2021 to 2024). A parasitic infection caused by Coccidia. "A downregulation in mRNA expression of FABP2 occurred in compromised gut barrier chickens (challenged with coccidiosis vaccine) along with decreased MUC2 and occludin expression, which may indicate an association between FABP2 and gut integrity in chickens." (PMID 34671361, 2021).
colon cancer (2 papers, 2020 to 2024). "Transcriptome sequencing analysis of patient colon cancer tissues revealed that Smad4 expression was negatively correlated with Fabp2 and SCD1 expression." (PMID 39664586, 2024).
E. coli infection (2 papers, 2022 to 2024). "After LAB addition, FABP2 expression returned to control group levels, suggesting that LAB positively affects abnormal FABP2 expression caused by E. coli infection." (PMID 38390621, 2024). "Regarding E. coli infection, the lower expression levels of MUC-2 and FABP-2 genes in infected and untreated birds were associated with excessive gut inflammation." (PMID 35812892, 2022).
eczema (2 papers, 2021 to 2022). "There was lower risk of ever eczema for increasing FABP2 at 1 year (OR: 0.49, 95% CI: 0.24–1.00, logistic regression)." (PMID 34194728, 2021). "Although LBP and FABP2 did not correlate with eczema, increased bacterial abundance was associated with increased serum FABP2." (PMID 34194728, 2021).
gastric cancer (2 papers, 2021 to 2025). A primary or metastatic malignant neoplasm involving the stomach. "Recent studies have found that the tumor frontier region (Stroma AReactive Invasion Front Areas, SARIFA) in gastric cancer is associated with the abnormal expression of lipid metabolism-related genes (including FABP2, FABP4)." (PMID 40717587, 2025). "Increased expressions of PPARA1, ACAA1, FABP1, and FABP2 were detected in SNU-478 ampullary cancer cells compared to pancreatic cancer cells (Pan1 and MIA-Pan2) and gastric cancer cells (AGS) by qPCR." (PMID 33390794, 2021).
hyperlipidemia (2 papers, 2020 to 2022). "As for the negatively correlated proteins (Fabp2, Slc27a4, Me1), they are mainly involved in lipid uptake and lipid biosynthesis, which indicates hyperlipidemia might inhibit the formation of HDL-c." (PMID 36234935, 2022).
ischemic stroke (2 papers, 2023 to 2025). A stroke disorder caused by obstruction of blood flow to the brain, due to thrombotic (local blood clot formation) or embolic (due to a blood clot or other material traveling from another site) event. "Here we evaluated the associations between alleles of FABP1 and FABP2 genes and ischemic stroke risk in 251 Chinese Han patients." (PMID 37091779, 2023). "The present study aimed to determine the association between FABP1 or FABP2 and ischemic stroke." (PMID 37091779, 2023). "Association between different FABP2 genotype and risk factors for ischemic stroke." (PMID 37091779, 2023). "We observed the associations between FABP2 rs1799883 polymorphisms and ischemic stroke." (PMID 37091779, 2023). "As we did not measure the fatty acid levels in patients with ischemic stroke, the relationship between fatty acid levels and the FABP2 Ala54Thr genotype requires further validation." (PMID 37091779, 2023).
mood disorder (2 papers, 2018 to 2024). A cognitive disorder a disturbance in which the person's mood is hypothesized to be the main underlying feature. "The patients with mood disorders had also higher levels of plasma LPS, zonulin and fatty-acid binding protein 2 (FABP2) which reflected gut permeability." (PMID 29710769, 2018).
schizophrenia (2 papers, 2020 to 2024). A major psychotic disorder characterized by abnormalities in the perception or expression of reality. "Among dozens of high-confidence links, we found new evidence for a causal role of a protein called SHPS1 in schizophrenia, and of another protein (FABP2) in heart disease." (PMID 32628676, 2020).
Stillbirth (2 papers, 2022). Death of the fetus in utero after at least 22 weeks of gestation. "Moreover, FABP2 and zonulin were positively correlated with most of the stillbirth-associated bacterial species." (PMID 36741405, 2022).
acne (1 paper, 2023). An inflammatory process of the sebaceous glands which is characterized by comedones, nodules, papules and/or pustules on the skin. "This reduction in FABP-2 also correlates with a decrease in sebum production and with an improvement in clinical acne." (PMID 36769543, 2023). "Regardless, there was a trend toward reducing the FABP-2 levels after probiotic supplementation, suggesting that the probiotics may normalize or reduce FABP-2 levels in those with acne." (PMID 36769543, 2023). "Furthermore, the FABP-2 marker was elevated at baseline for those with acne and had a reducing trend after probiotic supplementation in this group." (PMID 36769543, 2023). "The LPS and FABP-2 results suggest that “leaky gut” may be present in those with acne and that probiotic exposure may normalize intestinal barrier function." (PMID 36769543, 2023). "Therefore, it is possible that the elevated FABP-2 may represent a higher fat intake or a greater sensitivity to fat at the gut level of those with acne." (PMID 36769543, 2023). "When the data were evaluated for shifts from probiotic exposure in those with acne, there were no significant shifts in FABP-2, TNF-alpha, or LPS, but there was a trend toward an increase in zonulin (p = 0.052)." (PMID 36769543, 2023). "When comparing the acne group against the no acne group, there was a trend toward a decrease in FABP-2 (p =0.14) and a trend toward an increase in zonulin (p = 0.099) after probiotic exposure." (PMID 36769543, 2023). "However, FABP-2 levels were elevated in those with acne relative to those without acne (p = 0.088) prior to any interventions." (PMID 36769543, 2023).
acute appendicitis (1 paper, 2022). "Before surgery, the FABP2 concentration was greater in Group A than in Group B suggesting that the intestinal mucosal dysfunction in the patients with chronic cholecystitis was more serious than that in the patients with acute appendicitis." (PMID 36465208, 2022).
alcohol dependence (1 paper, 2023). Physical and psychological dependence on alcohol. "Compared to the control group, the LPS and FABP2 in alcohol dependence mice serum increased, while FMT significantly decreased the change levels, suggesting the reparative impact of FMT on intestinal leakage." (PMID 38249454, 2023).
alcohol liver disease (1 paper, 2024). "Gut permeability biomarkers (FABP2, LBP, and zonulin) did not change, but were associated with comorbid pathologies (alcohol liver disease and pancreatitis)." (PMID 38792318, 2024).
ampullary adenocarcinomas (1 paper, 2021). "Increased expressions of ACAA1 (acetyl-CoA acyltransferase 1), FABP1 (fatty acid-binding protein 1), PPARA, and FABP2 genes were seen in ampullary adenocarcinomas compared to pancreatic adenocarcinomas." (PMID 33390794, 2021).
cataract (1 paper, 2014). Partial or complete opacity of the crystalline lens of one or both eyes that decreases visual acuity and eventually results in blindness. "Frequencies of Ala54Ala, Ala54Thr and Thr54Thr genotypes in FABP2 gene in cataract cases and controls were 50.76%, 39.23%, 10% and 25.42%, 61.86%, 12.71% respectively." (PMID 25606413, 2014). "In the present study, we examined the association between FABP2 and PPARG2 gene polymorphisms in cataract cases among North Indian population." (PMID 25606413, 2014).
chronic viral hepatitis (1 paper, 2024). "A previous report observed that patients with chronic viral hepatitis exhibited elevated plasma levels of FABP-2 when compared to the control groups." (PMID 38339096, 2024).
endometriosis (1 paper, 2025). The growth of functional endometrial tissue in anatomic sites outside the uterine body. "Machine learning identified SSTR5, CASP3, FABP2, and SYK as critical targets, contributing to a nomogram that demonstrated good predictive performance for endometriosis risk." (PMID 39754173, 2025). "These correlation analyses underscore the significant involvement of the key anti-endometriosis targets (SSTR5, CASP3, FABP2, and SYK) in modulating immune cell infiltration and immune-related pathways." (PMID 39754173, 2025). "The correlation between gene expression of the four key anti-endometriosis targets (SSTR5, CASP3, FABP2, and SYK) and immune cell infiltration was analyzed." (PMID 39754173, 2025). "Four common key targets (SSTR5, CASP3, FABP2, and SYK) were identified across all three machine learning methods, suggesting their crucial role as therapeutic targets for the anti-endometriosis effects of monoterpene glycosides from Paeonia lactiflora." (PMID 39754173, 2025). "The expression profiles of the four key anti-endometriosis targets (SSTR5, CASP3, FABP2, and SYK) were analyzed." (PMID 39754173, 2025).
glioma (1 paper, 2019). A benign or malignant brain and spinal cord tumor that arises from glial cells (astrocytes, oligodendrocytes, ependymal cells). "In a glioma model, FASN expression and lipid synthesis were high in patient-derived TICs, along with glioma TIC markers SOX2, fatty acid binding protein-2 (FABP2) and nestin, and FASN inhibition led to downregulation of these markers as well as decreased viability and invasivity." (PMID 31661927, 2019).
hip fracture (1 paper, 2025). Traumatic or pathological injury to the hip in which the continuity of either the femoral head, femoral neck, intertrochanteric or subtrochanteric regions is broken. "A higher level of serum LPS but not FABP2 was found in hip fracture patients with low ASMI." (PMID 39829204, 2025).
Hypercholesterolemia (1 paper, 2021). An increased concentration of cholesterol in the blood. "The association between an improvement in VO2peak (≥ 5 mL/kg/min) and reduction in FABP2 remained significant following adjustment for hypercholesterolemia in multivariable linear regression analysis with FABP2 as the dependent variable (B = -0.446, p = 0.018)." (PMID 34797867, 2021).
liver cancer (1 paper, 2014). An epithelial or non-epithelial malignant neoplasm that arises from the liver. "Previously it was reported that treatment of mouse primary hepatocytes with peroxisomes proliferators (including Wy14643) for 24 hours led to upregulation of 11 genes related to liver cancer (i.e. Angptl4, Bnip3, Dbi, Fabp1, Fabp2, Fasn, HifIa, Lgals3, Ly6d, Mgll, SerpineI)." (PMID 25511156, 2014).
liver cirrhosis (1 paper, 2023). "High FABP2 levels is significantly associated with increased mortality from variceal bleeding in patients with liver cirrhosis." (PMID 38138294, 2023). "This current study demonstrated that serum FABP2 levels were significantly higher in HCC patients compared with healthy controls that might be associated with background of liver cirrhosis in most HCC cases." (PMID 38138294, 2023). "FABP2 concentration in plasma were found to be different in pattern and absolute levels but as well elevated in liver cirrhosis." (PMID 38138294, 2023). "Recent studies have demonstrated that fecal FABP2 levels are significantly increased in cases of liver cirrhosis and correlate with disease severity." (PMID 38138294, 2023).
mental disorder (1 paper, 2022). A disease that has its basis in the disruption of mental process. "The involvement of calprotectin, zonulin, LBP and IFABP/FABP2 in the study of mental disorders remains an open matter, given that inflammatory processes are known to be involved in the aetiology of affective disorders." (PMID 36079050, 2022).